ADAMTS13 (ADAM metallopeptidase with thrombospondin type 1 motif 13)
Diseases named in the same sentence as ADAMTS13 in open-access papers (continued):
Sharing a sentence is not in itself a finding about the gene and the disease.
endothelial dysfunction (28 papers, 2013 to 2026). In vascular diseases, endothelial dysfunction is a systemic pathological state of the endothelium (the inner lining of blood vessels) and can be broadly defined as an imbalance between vasodilating and vasoconstricting substances produced by (or acting on) the endothelium. "envenoming, only few case reports have previously evaluated the levels of ADAMTS13, the main biological factor of endothelial dysfunction and thrombosis risk associated with this syndrome." (PMID 41160661, 2025). "The vWF ADAMTS13 axis is likely impaired because of endothelial dysfunction caused by the SARS- CoV-2 -induced activation of endothelial cells, leading to a significantly higher and independent risk of preterm delivery in this setting." (PMID 35189860, 2022). "Altered shear stress, turbulent flow, and endothelial dysfunction promote thrombus formation and modulate systemic hemostasis via platelet activation and the von Willebrand factor-ADAMTS13 axis." (PMID 41977327, 2026). "By using a thrombin generation test with TM, alongside assessments of VWF antigen and ADAMTS-13 activity, we seek to investigate the extent of coagulation abnormalities and endothelial dysfunction in PCS patients." (PMID 39941459, 2025). "Future clinical trials evaluating endothelial-targeted therapies in ACLF should consider stratifying patients based on baseline levels of endothelial dysfunction markers, such as vWF and ADAMTS13." (PMID 40429533, 2025). "We identified inflammatory and endothelial dysfunction markers (ADAMTS-13, TNF-α, GDF-15, MIP-1β, VEGFA, MPO, and MIC-1) that cooperate in a common pathway and are increased in FD patients’ plasma samples." (PMID 38892211, 2024). "Patients with LVNC and HFpEF had endothelial dysfunction, expressed by a lower ADAMTS13 level and ADAMTS13/vWF ratio, and the overexpression of Galectin-3." (PMID 37297827, 2023). "For all patients, we performed CMR, speckle tracking echocardiography (STE), and biomarker assessment for HFpEF (NT-proBNP), for myocardial fibrosis (Galectin-3), and for endothelial dysfunction [ADAMTS13, von Willebrand factor, and their ratio]." (PMID 37297827, 2023). "Endothelial dysfunction biomarkers correlated positively with compact myocardium mass (R = 0.588 for ADAMTS13, p = 0.01; and R = 0.824 for the ADAMTS13/vWF ratio, p < 0.001)." (PMID 37297827, 2023). "Von Willebrand factor (VWF), and a disintegrin and metalloproteinase with thrombospondin motifs 13 (ADAMTS-13), are strong markers of endothelial dysfunction." (PMID 34573989, 2021). "Elevation of VWF and potential reduction in ADAMTS13 essentially represent biomarkers of endothelial dysfunction, as most recently typified in COVID-19." (PMID 34564132, 2021). "Nonetheless, COVID-19 disease progression is consistent with endothelial dysfunction and increased plasma VWF levels and VWF:AG/ADAMTS13 activity ratios are associated with COVID-19 disease severity and reported to be a predictor of morbidity and mortality." (PMID 35087853, 2021). "VWF, including its production and binding to GPIb, collagen and Glycoprotein IIbIIIa, as well as ADAMTS13, have been well recognized as potential therapeutic targets within management of vascular events and endothelial dysfunction." (PMID 34564132, 2021). "Aging and obesity independently contribute toward an endothelial dysfunction that results in an imbalanced VWF to ADAMTS13 ratio." (PMID 35087853, 2021). "This interaction suggests that the effect of ADAMTS13 is mainly present in individuals with advanced endothelial dysfunction." (PMID 27787621, 2017). "Based on the evidence that these biomarkers are associated with endothelial dysfunction and hypercoagulability, this study aimed to investigate the relationship among VWF, ADAMTS13, and D-Dimer with different levels of renal dysfunction in DM1 patients." (PMID 26168189, 2015).
endothelial dysfunction (continued). "VWF/ADAMTS13 and ADAMTS13 activity/ADAMTS13 Ag ratio have also been described as markers of endothelial dysfunction and a reduced activity of ADAMTS13 was shown to be associated with renal disease in patients with type 2 diabetes mellitus (DM2)." (PMID 26168189, 2015). "ADAMTS13 may alleviate DN by inhibiting modulating ferroptosis through the regulation of mitophagy, thereby ameliorating endothelial dysfunction." (PMID 41912450, 2026). "In addition to TM, other markers of endothelial health, such as von Willebrand factor activity and ADAMTS-13 activity, are important in assessing endothelial dysfunction." (PMID 39941459, 2025). "Based on these observations, we hypothesize that recombinant human (rh) ADAMTS13 might mitigate diabetes-induced retinal injury by improving endothelial dysfunction and inhibiting inflammation." (PMID 39851513, 2025). "This is the first study that showed lower levels of ADAMTS13 in LVNC patients, with a reduced ADAMTS13/vWF ratio, suggesting that endothelial dysfunction may play an important role in the pathogenesis of LVNC." (PMID 37297827, 2023). "Endothelial dysfunction, expressed by the lower ADAMTS13 and ADAMTS13/vWF ratio, may play an important role in the mechanism of HFpEF in patients with LVNC." (PMID 37297827, 2023). "Such strategies may include targeting the upregulated VWF or decreased ADAMTS13 activity in patients with cardiac failure, in order to halt persistent endothelial dysfunction and disease progression." (PMID 34564132, 2021). "The present study defines VWF/ADAMTS13 axis parameters as markers of endothelial dysfunction, along with thrombin and plasmin generation as predictors of thrombosis and fibrinolysis, based on two important risk factors known to predict poor outcome in COVID-19 infection: increased age and obesity." (PMID 35087853, 2021). "In children with cerebral silent infarcts, ADAMTS13 Ag and t-PA:Ag were significantly lower suggesting endothelial dysfunction, while several other coagulation variables (D-dimer, P-selectin, TAT, F1+2) tended to be higher suggesting a trend to enhanced clotting activation." (PMID 24205317, 2013). "Based on these findings, evaluating both the VWF/ADAMTS13 axis, along with thrombin and plasmin generation, could provide insight into the extent of endothelial dysfunction as well as the plasmatic imbalance in coagulation and fibrinolysis potential, particularly for at-risk patient populations." (PMID 35087853, 2021). "This study investigates hypercoagulability and endothelial dysfunction in PCS through thrombin generation and the von Willebrand factor (VWF)/ADAMTS13 axis." (PMID 39941459, 2025). "Furthermore, if endothelial dysfunction is validated in future large-scale studies, ADAMTS13 level and the ADAMTS13/VWF ratio might be used in clinical practice to monitor the progression of endothelial dysfunction, and these biomarkers might become other therapeutical targets in patients with LVNC." (PMID 37297827, 2023). "For instance, ADAMTS13 deficiency has been observed in severe malaria, particularly in cerebral manifestations, which may contribute to the pathophysiology of complicated malaria by impairing the regulation of von Willebrand factor (VWF) and promoting endothelial dysfunction." (PMID 37638001, 2023). "What is more, patients with HFRS had higher markers of endothelial dysfunction (Angiopoetin-2, sVCAM-1, PAI-1, ADAMTS13, d-dimer, sP-Selectin, fibrinogen, vWF, sE-Selectin, sPECAM-1, TF and TM) than CCHF patients." (PMID 31357521, 2019).
endothelial dysfunction (continued). "Various markers of endothelial injury have been investigated in CAR-T cell recipients, including markers of complement activation, such as soluble C5b-9, endothelial dysfunction (angiopoietin-2, VCAM1, ICAM-1), inflammation, and thrombosis (von Willebrand antigen, ADAMTS13, thrombomodulin)." (PMID 40940973, 2025). "Since VWF, ADAMTS13 activity and D-Dimer levels are also elevated in DM2 patients with nephropathy, we believe that endothelial dysfunction and hypercoagulability may play an important role in the progression of renal dysfunction in both DM1 and DM2." (PMID 26168189, 2015). "The protease, a disintegrin and metalloproteinase with thrombospondin type 1 motif member 13 (ADAMTS13), known to cleave only the von Willebrand factor (VWF), has powerful regulatory effects on microvascular platelet adhesion, thrombosis, inflammation, and endothelial dysfunction." (PMID 39851513, 2025). "Consistent findings contributing to the hypercoagulability include elevated von Willebrand factor secondary to endothelial dysfunction; elevated fibrinogen and FVIII, both acute‐phase proteins; reduced thrombomodulin; and reduced ADAMTS‐13 with altered von Willebrand factor/ADAMTS‐13 ratio." (PMID 35733235, 2022).
autoimmune disease (27 papers, 2008 to 2025). A disorder resulting from loss of function or tissue destruction of an organ or multiple organs, arising from humoral or cellular immune responses of the individual to their own tissue constituents. "Compared with patients with ADAMTS13 ≥ 10%, those with severe ADAMTS13 deficiency were younger, with a higher proportion of women, autoimmune disorders and a lower proportion of cancer." (PMID 35739601, 2022). "The opposite impact of the IgG4 subclass and Fc-FcγR interaction on the pathogenic function of autoantibodies in anti-ADAMTS13 and anti-Dsg1 autoantibodies suggests that these autoantibodies have different modes of action in IgG4-mediated autoimmune diseases." (PMID 35920621, 2022). "Patients with severe ADAMTS13 deficiency were younger, mainly women, with a higher prevalence of autoimmune disorders and a lower prevalence of cancer." (PMID 35739601, 2022). "Since iTTP is also an autoimmune disease caused by auto-antibodies against ADAMTS13, a modulatory effect on the B cell production of antibodies probably would correlate with a more durable remission." (PMID 33195351, 2020). "TTP occurs as hereditary or autoimmune disease and is the phenotype of ADAMTS13 deficiency-associated VMTD." (PMID 30127669, 2018). "Acquired TTP, the more common form, is usually an autoimmune disease caused by antibodies against ADAMTS13 protein." (PMID 24288641, 2013). "Three distinct forms of TTP were observed, including an autoimmune disease with anti‐ADAMTS13 IgG (75%), an acquired disease of unknown origin (22%) and an inherited disease (Upshaw–Schulman syndrome) with mutations of the ADAMTS13 gene (3%)." (PMID 40206570, 2025). "Most of the cases are the result of acquired deficiency of ADAMTS13, for which the exact etiology is unknown but reported to be related to various autoimmune disorders, infections, and medications." (PMID 34552799, 2021). "A similar scenario has been described in other autoimmune diseases mediated by IgG4, like in idiopathic thrombotic thrombocytopenic purpura, where an IgG4 subclass switching is associated with increased inhibition of ADAMTS13 enzymatic activity by anti-ADAMTS13 IgG4 antibodies." (PMID 32083137, 2019). "It is an autoimmune disorder mediated by antibodies against ADAMTS13 (a disintegrin and metalloproteinase with thrombospondin motifs 13), a von Willebrand factor-cleaving protease, leading to its severe functional deficiency." (PMID 40625480, 2025). "While our study of anti-ADAMTS13 autoantibodies supports the notion that switching to immune-inert IgG4 subclass is a protective mechanism in IgG4-mediated autoimmune diseases, our analysis of anti-Dsg1 autoantibodies suggests the opposite." (PMID 35920621, 2022). "Acquired TTP is considered a specific autoimmune disease characterized by antibodies, usually immunoglobulin G, directed against ADAMTS13." (PMID 29871663, 2018). "Last, it is noteworthy that 31 out of 54 patients with a detectable ADAMTS13 activity had a moderate decrease in the protein activity that ranged from 20% to 50%, as it was reported in various autoimmune diseases or other conditions." (PMID 20436664, 2010). "In contrast, in a study of the ADAMTS13 levels of 15 patients with autoimmune disease-associated TMA (SLE, APLS, thyroiditis, psoriasis, Crohn disease), seven had undetectable ADAMTS13 levels, five had normal levels, and three had intermediate levels." (PMID 17906963, 2008). "However, the importance of decreased ADAMTS13 levels in the plasma of MS patients has not been fully assessed, which prompted us to test the role of ADAMTS13 in autoimmune diseases, such as EAE." (PMID 32075652, 2020). "The underlying ADAMTS13 deficiency is caused by ADAMTS13 mutations in the rare, congenital form of TTP, whereas the more common, acquired form of TTP is an autoimmune disease, in which autoantibodies against the ADAMTS13 enzyme are responsible for its deficiency." (PMID 30061898, 2018).
autoimmune disease (continued). "Idiopathic TTP is an autoimmune disease caused by severe deficiency of the von Willebrand factor (VWF) cleaving protease, a disintegrin-like and metalloprotease with thrombospondin type 1 repeats (ADAMTS13), due to inhibitory anti-ADAMTS13 antibodies." (PMID 26022055, 2015). "However, AA-VMTD is autoimmune disease resulting from ADAMTS13 antibody." (PMID 30127669, 2018). "However, as DM1 is an autoimmune disease, auto-antibodies against ADAMTS13 could also partially explain the imbalance between ADAMTS13 activity and ADAMTS13 Ag levels, by inhibiting ADAMTS13 activity." (PMID 26168189, 2015). "As previously reported in the literature, patients with severe ADAMTS13 deficiency were more likely to be young, female, with a history of autoimmune diseases but no previous cancer as compared with those with ADAMTS13 ≥ 10%." (PMID 35739601, 2022). "Notably, studies showed that although iTTP considers an autoimmune disease, ADAMTS-13 inhibitors are not easily detectable in many patients, which was not the case in our patient." (PMID 36709264, 2023).
hemolytic-uremic syndrome (26 papers, 2009 to 2025). Acute kidney injury associated with microangiopathic hemolytic anemia and thrombocytopenia. "A subsequent normal ADAMTS13 activity level and positive stool sample for Escherichia coli O157:H7 confirmed the diagnosis of Shiga toxin-associated hemolytic uremic syndrome." (PMID 27301547, 2016). "Plasma exchange was started empirically until ADAMTS13 activity returned normal (120%), and she was further commenced on eculizumab after an atypical hemolytic uremic syndrome (aHUS)/TMA/Complement 3 Glomerulopathy (C3G) gene panel was sent." (PMID 40115863, 2025). "ADAMTS13 activity was later found to be within normal limit, hence diagnosis of atypical hemolytic uremic syndrome was strongly considered at that time and she was immediately treated with anti-C5 humanized monoclonal antibody (eculizumab)." (PMID 28101432, 2017). "MAHA with normal ADAMTS13 activity level consists of a spectrum of disorders that includes hemolytic uremic syndrome (HUS)." (PMID 27301547, 2016). "ADAMTS13 activity was measured at 22% (N >20%), leading to the diagnosis of hemolytic-uremic syndrome (HUS) while tests for Shiga toxins were negative." (PMID 41137256, 2025). "coli) hemolytic uremic syndrome were excluded by a normal ADAMTS-13 and negative E." (PMID 34549020, 2021).
acute kidney injury (25 papers, 2010 to 2025). Sudden and sustained deterioration of the kidney function characterized by decreased glomerular filtration rate, increased serum creatinine or oliguria. "Comparable observations have been made in models of acute kidney injury, diabetic retinopathy, rheumatoid arthritis, or sickle cell disease, where loss of ADAMTS13 increased inflammation, and recombinant ADAMTS13 exerted anti-inflammatory effects." (PMID 41009700, 2025). "Patients with severe ADAMTS13 deficiency also showed a trend for a higher proportion of bleeding (42% vs 13%) and cardiovascular signs and symptoms (11% vs 0%) and a lower proportion of renal failure (11% vs 38%), compared with those with ≥ 10%." (PMID 35739601, 2022). "The differential diagnosis between these two paradigmatic forms of TMA is based on the presence of either frank renal failure in HUS or a severe deficiency (<10%) of the zinc-protease ADAMTS13 (a disintegrin and metalloproteinase with a thrombospondin type 1 motif, member 13) in TTP." (PMID 31337190, 2019). "The need for dialysis, reflecting renal failure, was not significantly different between the three groups although the association of both DIC and ADAMTS13 deficiency <30% exhibited more renal failure than both of the other groups with a borderline significance (P = 0.05)." (PMID 24238574, 2013). "Since the mean age at TTP diagnosis is usually the fourth decade, this result suggests that older patients may be a risk factor of developing severe renal failure despite ADAMTS13 deficiency." (PMID 20436664, 2010). "Interestingly, we noted that all 3 misclassified patients with a severe renal failure who finally had a deficient ADAMTS13 activity were ≥55-year-old." (PMID 20436664, 2010). "At hospital admission, the clinical and laboratory characteristics of patients largely overlapped, with clinical manifestations better differentiating patients with ADAMTS13 activity below and above 10% being hemorrhagic symptoms and renal failure." (PMID 35739601, 2022). "ADAMTS-13 plays an important role in acute kidney injury (AKI), but the mechanism of cisplatin (CP) induced AKI remains unclear." (PMID 34666603, 2021). "However, a retrospective study of 92 cases of TTP with low ADAMTS-13 activity (< 10%) found that more than half of the patients had acute kidney injury, with nearly half experiencing stage 3 acute kidney injury and a quarter requiring renal replacement therapy." (PMID 40390002, 2025). "We have demonstrated that moderately reduced ADAMTS13 activity correlates with the risk of severe manifestations of STEC-HUS in children; the rate of developing multiple organ failure, cerebral disorders, pulmonary edema, and acute kidney injury with the need for dialysis increases." (PMID 38002352, 2023). "Our paper explores the mechanism of CP induced AKI and confirms that ADAMTS-13 regulates Nrf2 signaling pathway to inhibit ferroptosis, thereby ameliorating CP-induced acute kidney injury." (PMID 34666603, 2021). "However, within patients with features of aHUS (i.e., TMA patients with renal failure, a detectable ADAMTS13 activity and no associated STEC), distinct diseases with specific pathophysiological mechanisms, therapeutic modalities and prognosis may be further individualized." (PMID 28542627, 2017). "We found microangiopathic anemia, lymphopenia, elevated lactate dehydrogenase, progressive acute renal failure, negative direct antiglobulin test, and normal activity of ADAMTS13." (PMID 27266265, 2016).